IL2 (interleukin 2)
Diseases named in the same sentence as IL2 in open-access papers (continued):
Sharing a sentence is not in itself a finding about the gene and the disease.
renal cell carcinoma (continued). "A phase I/II clinical trial (NCT01038778) has studied the combination of entinostat (a selective HDAC1 and HDAC3 inhibitor) and aldesleukin (interleukin 2) in renal cell carcinoma patients." (PMID 33024443, 2020). "TNF-related apoptosis-inducing ligand (TRAIL) and IL-2 have also being transfected into TILs isolated from renal cell carcinoma (RCC) resulting in improved cytotoxicity activity." (PMID 33680923, 2020). "In the 1980s, high-dose interleukin-2 (IL-2) was used successfully in renal cell cancer, producing a prolonged and durable response along with overall survival benefit in a small subset of patients." (PMID 32245016, 2020). "Using high-dose IL-2 for patients with renal cell carcinoma, 14% of patients (255 patients total) had an objective response, while 12 patients experienced a complete response." (PMID 30842774, 2019). "Considering the Food and Drug Administration approval, patients with renal cell carcinoma are treated with high-dose recombinant IL-2; however, its use has a high incidence rate of cardiotoxicity." (PMID 30386232, 2018). "Whole blood samples were collected prior to the first dose and after the last dose of treatment cycles 1 and 2 from a cohort of renal cell carcinoma patients receiving treatment with HD IL-2." (PMID 30400835, 2018). "Numerous animal models have shown that combining radiotherapy with IL-2 has a synergistic antitumor effect and has been shown to be useful clinically in oral cancer, renal cell carcinoma, and prostate cancer." (PMID 30619280, 2018). "It was not until 1992 that the first immunotherapy was approved by the FDA; high dose interleukin-2 (HD IL-2), for renal cell carcinoma (RCC)." (PMID 29285416, 2017). "Another case report describes a patient with renal cell carcinoma treated with IL-2 who subsequently developed MG, myositis, and insulin-dependent diabetes mellitus." (PMID 27826593, 2016). "In renal cell carcinoma, endogenous CXCL9 was closely implicated in the antitumor effects that were produced by IL‐2 64 and IL‐12 (also producing CXCL10) 65 by inhibiting tumor angiogenesis and infiltration of CD8+ T lymphocytes, respectively." (PMID 27726306, 2016). "We previously reported that the expanded FoxP3+ Treg subset from peripheral blood of untreated renal cell carcinoma patients and also following IL-2 treatment co-express Helios." (PMID 26885615, 2016). "In contrast, administration of IL-2 inhibited autophagic flux in patients with melanoma and renal cell carcinoma." (PMID 25590298, 2015). "We investigated a combination therapy of YM155 and interleukin-2 (IL-2) in a mouse model of renal cell carcinoma (RCC)." (PMID 26023798, 2015). "With properly trained practitioners and nursing staff, IL-2 should still be considered a first-line treatment for patients with renal cell carcinoma." (PMID 26557408, 2015). "A progress report on the treatment of 157 patients with advanced cancer, using LAK cells and IL-2 or high-dose IL-2 alone, included 36 patients with renal cell carcinoma." (PMID 28326252, 2014). "At the Levine Cancer Institute, we have treated 104 patients with advanced renal cell carcinoma with high-dose IL-2." (PMID 28326252, 2014). "The initial stimulus for writing this review was inspired by the observations made by two of the authors (DTA, CAD) of a scurvy-like condition in a renal cell carcinoma patient treated with IL-2." (PMID 24884532, 2014). "Immunotherapy with high-dose IL-2 had been the mainstay of systemic treatment for advanced renal cell carcinoma until the development of agents inhibiting the VEGF and mTOR pathways." (PMID 28326252, 2014). "As a single agent at high dose IL-2 induces remissions in a minority of patients with renal cell carcinoma (RCC) and metastatic melanoma, with an unclear mechanism of action." (PMID 25054077, 2014).
renal cell carcinoma (continued). "The immunological mechanism mediated by T cells is the main therapeutic target in the treatment of renal cell carcinoma (RCC) with interleukin (IL)-2 and interferon (IFN)-α." (PMID 24765159, 2014). "This concept of immunotherapeutic timing and synchronisation has been extended and reviewed recently in renal cell cancer therapy using IL-2." (PMID 27437102, 2014). "In earlier studies cytokine therapy with interferon-alpha or interleukin-2 (IL-2) was shown to induce objective responses, although only achieving durable survival rates in a minority of patients with renal cell carcinoma." (PMID 23878753, 2013). "In this study, the significance of the DC vaccine combined with IL-2 in renal cell carcinoma and breast cancer patients is presented regarding the relevance between the clinical and immunological responses." (PMID 22013914, 2011). "Six patients with renal cell carcinoma and four patients with breast cancer were treated with 5 × 107 DCs and 14 consecutive IL-2 injections in a single vaccination protocol, and all patients received two vaccinations at a one-month interval." (PMID 22013914, 2011). "We conducted a non-randomised controlled phase II trial to investigate the role of preoperative administration of interleukin-2 (IL-2) in patients with renal cell carcinoma undergoing tumour nephrectomy." (PMID 17031403, 2006). "Specifically, massive production of chemoattractants, has been demonstrated by quantitative methods (multiplex protein array/Searchlight) in renal cell carcinoma (RCC) patient serum after high dose IL-2 therapy." (PMID 16433902, 2006). "As a result, developing and assessing drugs that block the generation of oxygen radicals as an adjunct to IL-2 is a viable therapeutic opportunity in renal cell cancer." (PMID 16434984, 2006). "Preclinical efficacy studies in a renal cell carcinoma, murine model also showed that direct intra-tumoral administration of an IL-2 plasmid DNA/DMRIE/DOPE complex resulted in the generation of tumor specific lymphocytes and complete tumor regression." (PMID 15329148, 2004). "In conclusion, we achieved 5.7% of objective response and 40% of stabilisation including 11.4% prolonged stabilisation >8 months with IL-2, IFNα, 5-FU in patients with renal cell carcinoma in whom previous first-line immunotherapy failed." (PMID 14676797, 2003). "RENCA-IL-2 (Murine Renal Cell Carcinoma transfected with murine IL-2 gene) cells were rejected by immunocompetent (but not T-cell deficient) Balb/c mice, which developed ‘immunity’ to subsequent parental RENCA tumour cell challenge." (PMID 10993655, 2000). "Sixty patients with recurrent renal cell carcinoma (RCC) who had previously undergone a nephrectomy were randomized to receive three cycles of IL-2 or IL-2 with IFN-alpha2b." (PMID 9703284, 1998). "Recent clinical studies have suggested that the combination of subcutaneous recombinant human interleukin 2 (rIL-2) and interferon alpha (rIFN-alpha) is especially promising in advanced renal cell carcinoma." (PMID 8519672, 1995). "In a phase I trial the toxicity and immunomodulatory effects of combined treatment with intravenous (i.v.)bispecific monoclonal antibody BIS-1 and subcutaneous (s.c.)interleukin 2 (IL-2) was studied in renal cell cancer patients." (PMID 7917912, 1994). "Interleukin-2 (IL-2) is now registered for the treatment of renal cell carcinoma in a number of European countries." (PMID 1419609, 1992). "IL-2 treatment can confer durable response in melanoma and renal cell carcinoma (RCC) patients." (PMID 40165901, 2025). "In 1992, interleukin 2 (IL-2) was registered as a treatment for renal cell carcinoma patients." (PMID 40486521, 2025). "For example, renal cell carcinoma can be treated with high doses of interleukin-2 (IL-2)." (PMID 40556945, 2025). "IL-2 timing affects survival in renal cell carcinoma patients, favoring morning or nighttime doses." (PMID 39744625, 2024).
renal cell carcinoma (continued). "HD IL-2 is FDA-approved for the treatment of renal cell carcinoma and other cancers." (PMID 39315105, 2024). "In addition, it has been reported that anti-CD69 antibodies can enhance the anti-tumor effects against the murine renal cell carcinoma (Renca) cell line by promoting T cell proliferation, IL-2 expression, and cytotoxicity." (PMID 37880277, 2023). "IL-2 can mediate tumor treatment in patients with renal cell carcinoma and metastatic melanoma." (PMID 30386232, 2018). "Ten cancer patients (Six renal cell carcinoma and four breast cancer patients) were treated in a phase I/II study with a vaccine composed of autologous dendritic cells (DCs) and IL-2 to evaluate the DC vaccine-related toxicity and antigen-specific immune alteration." (PMID 22013914, 2011). "Thus, high-dose IL-2 should remain in the armamentarium of the experienced clinical oncologist for advanced renal cell carcinoma." (PMID 24213115, 2011). "In particular, metastatic renal cell carcinoma (RCC) is frequently associated with elevated levels of IL-6, which have been reported to correlate with metastatic progression, poor prognosis, shorter survival, as well as poor response and high toxicity to IL-2 therapy." (PMID 20808314, 2010). "They used multiplexed protein array platforms to characterize the cytokine outburst that follows systemic IL-2 administration to patients with renal cell cancer undergoing high dose IL-2 therapy and correlated the findings with results obtained by transcriptional profiling." (PMID 16464241, 2006). "While renal-cell carcinoma responds poorly to single-agent chemotherapy or hormonal therapy, immunotherapies with subcutaneous (s.c.)recombinant interleukin-2 (IL-2) alone or in combination with s.c. recombinant interferon-α (INF-α) yielded significant therapeutic efficacy in renal-cell carcinoma." (PMID 12569375, 2003). "Both IFNα and IL-2 are exploited in the treatment of leukemia, renal cell carcinoma (RCC), and melanoma." (PMID 39519018, 2024). "Renal cell carcinoma (RCC), a common type of kidney cancer, is remarkably resistant to radiation therapy, chemotherapy and cytokine immunotherapy (including, interferon α/γ, interleukin-2) with a response rate of less than 20%." (PMID 36077036, 2022). "Currently, IL-2 is FDA-approved for treating adults with renal cell carcinoma (RCC) and malignant melanoma." (PMID 31847387, 2019). "Prior characterization of histologic features that are associated with tumor response to IL-2, showed that in patients with conventional renal cell carcinoma 21% (30/146 patients) respond to IL-2, whereas in non-clear cell subtypes, only 6% (1/17 patients) respond to IL-2." (PMID 29261796, 2017). "Renal cell carcinoma (RCC)-derived gangliosides reduce IL-2 and IFN-γ expression and increase apoptosis in T cells through NF-κB inhibition by reducing RelA(p65), p50, and antiapoptotic protein Bcl-xL." (PMID 26779443, 2015). "Renal cell carcinoma (RCC) is an immunologically responsive tumor and until recently, the mainstay for systemic therapy for advanced metastatic RCC was cytokine-based immunotherapy with interleukin 2 (IL-2) and interferon alpha (IFN-α)." (PMID 25901286, 2015). "Indeed, a preclinical surgical study using the renal cell carcinoma model has shown that anti-CD40 may be successfully combined with IL-2 to orchestrate effective DC and CD8 T cell response against distal tumours." (PMID 25518732, 2014). "Instead, interferon-α (IFN-α) and interleukin-2 (IL-2) are widely used for the treatment of metastatic renal cell carcinoma (RCC)." (PMID 17285137, 2007). "We conducted a prospective quality-of-life analysis during outpatient immunotherapy in 22 patients with progressive metastatic renal cell carcinoma (RCC) treated with subcutaneous interferon-α2a and subcutaneous interleukin-2." (PMID 12838299, 2003).
renal cell carcinoma (continued). "The phase 3 PIVOT-09 study unexpectedly failed to improve the likelihood of response or OS with nivolumab combined with an engineered IL-2 pathway agonist (bempegaldesleukin), compared with a control TKI in patients with untreated renal cell carcinoma (RCC)." (PMID 38539487, 2024). "In renal cell carcinoma (RCC), systemic interleukin-2 (IL-2) treatment activates the immune system, mainly by stimulating natural killer (NK) cells and T cells to kill tumor cells." (PMID 38789450, 2024). "Interleukin 2 (IL-2), initially discovered over 40 years ago, was approved by the FDA in 1992 for the treatment of renal cell carcinoma as an anti-cancer immunotherapy." (PMID 38352877, 2024). "In a renal cell carcinoma cell line, IFN-α, IL-2, and IFN-γ were found to upregulate B7-H4 expression." (PMID 35410218, 2022). "Cytokine-based immunotherapy, including interleukin 2 (IL-2) and recombinant human interferon-alpha 2a (IFN-α2a), is the first approved immunotherapy for renal cell carcinoma." (PMID 35686121, 2022). "This indicates that IL-2 and IFN-α have anti-tumor activity in renal cell carcinoma, and the triple immunotherapy that adds 5-fluorouracil to enhance the clinical therapeutic effect." (PMID 33767709, 2021). "Similarly, the IL-2-diphtheria toxin fusion protein denileukin diftitox was effective in patients with renal cell carcinoma (RCC) but had an adverse effect in metastatic melanoma." (PMID 29463952, 2017). "Based on its remarked efficacy in mice, cancer patients bearing renal cell carcinoma (RCC) and melanoma were administered high doses of IL-2 in order to increase antitumor immunity." (PMID 28083070, 2016). "In renal cell carcinoma (RCC), it was reported that high‐dose IL‐2 treatment in 20 patients elevated the plasma levels of CXCR3 ligands (CXCL9, CXCL10, and CXCL11), sequentially, forming an angiostatic environment." (PMID 27726306, 2016). "Biochemical parameters used with CRP (specifically in renal cell carcinoma) were: albumin (alone or as hypoalbuminemia), LDH, and interleukins (IL-6, IL-8, IL-2)." (PMID 26717416, 2015). "Clinical data indicate that autologous dendritic cell vaccines combined with IL-2 decreased TGF-β and CD4+CD25+ T cell levels and increased IL-12p70 levels in renal cell carcinoma or breast cancer patients." (PMID 25590298, 2015). "As an example of this, EXs purified from human kidney adenocarcinoma ACHN cells inhibited proliferation and induced apoptosis of Jurkat-immortalized T-cells while reducing in vitro interleukin-2 (IL-2), IL-6, IL-10 and interferon-γ production." (PMID 26539435, 2015). "In fact, an upregulation of IL2 by PKC has been reported and a phase II study was conducted combining IL2 with bryostatin 1 in patients with renal cell carcinoma." (PMID 24212628, 2011). "Temsirolimus was approved by the FDA in 2007 for the treatment of advanced renal cell carcinoma, a disease resistant to existing chemotherapies (IFN-α, IL-2)." (PMID 20298531, 2010). "Advanced renal cell carcinoma (RCC) is generally resistant to chemotherapy treatment, and immunotherapy with interferon-alpha and interleukin-2 (IL-2) as single agents or in combination with the chemotherapeutic agent 5-fluorouracil is currently used as systemic treatment for some cases." (PMID 16892042, 2006). "The schedule of IFN-α, IL-2 and PVI 5FU has significant activity in advanced renal cell cancer with manageable toxicity." (PMID 10993642, 2000). "No change in OS or RFS was observed in patients with renal cell carcinoma after surgery who obtained low-dose IL-2 and IFN-α adjuvants." (PMID 33767709, 2021). "ZOL with a low dose of IL-2 induced a transient γδ-T cell activation in patients with for example lung cancer or renal cell carcinoma, but this had no clinical effect on tumors." (PMID 34575700, 2021).
renal cell carcinoma (continued). "In patients with renal cell carcinoma that has spread to the pancreas, treatment with IFN-α and IL-2 used to be common; however, several new drugs, including temsirolimus, bevacizumab, sunitinib, and sorafenib, have proven to be effective in treating such diseases." (PMID 25256096, 2014). "Given that treatment with high-dose IL-2 is not applicable for many patients with advanced renal cell carcinoma, new immunotherapeutic approaches are being investigated." (PMID 28326252, 2014). "Given that immune-mediated regression had been observed in patients with renal cell carcinoma and the fact that renal cell carcinoma does not respond to chemotherapy, the earliest clinical investigations with IL-2, carried out at the NIH Surgery Branch, included renal cell carcinoma." (PMID 28326252, 2014). "However, comparison of therapy of IL-2 alone with combination of IL-2 with LAK cell has not shown any significant difference in response to renal cell carcinoma in clinical setting." (PMID 29854806, 2018). "For Renal Cell Carcinoma (RCC), thirty-seven patients with progressive, MUC1-positive tumors received TG4010 108 pfu/injection weekly for 6 weeks, then every 3 weeks until progression, when TG4010 was continued in combination with interferon-α2a and interleukin-2." (PMID 24212974, 2011). "Immunotherapy with interleukin 2 (IL-2) is not an effective anti-cancer treatment in the majority of patients with renal cell carcinoma (RCC), suggesting that the activation of cytotoxic T cells or NK cells may be impaired in vivo in these patients." (PMID 10408703, 1999). "Interleukin-2 (IL-2) induces durable objective responses in a small cohort of patients with metastatic renal cell carcinoma (RCC) but the antigen(s) responsible for tumor rejection are not known." (PMID 19128501, 2009). "Also, despite that a previous study in renal cell carcinoma patients suggested that monotherapy with IL-2 does not affect the frequency of cells with a MDSC phenotype, we cannot rule out that the IL-2 component may have contributed to the observed reduction of MDSCs." (PMID 30315349, 2019).